HIF1A (hypoxia inducible factor 1 subunit alpha)
Diseases named in the same sentence as HIF1A in open-access papers (continued):
Sharing a sentence is not in itself a finding about the gene and the disease.
pituitary adenomas (10 papers, 2015 to 2025). "We provide an overview of the general concepts, the potential factors associated with pituitary adenoma susceptibility for apoplectic events and the molecular mechanisms that could be involved such as HIF-1α/VEGF pathways and metalloproteinases activation, among others." (PMID 35955859, 2022). "More than a decade ago, the apoptotic protective function of HIF-1α in human pituitary adenoma cell line HP75 under hypoxic conditions via a knockdown experiment was observed." (PMID 30733705, 2019). "Hypoxia-inducible factor-1α (HIF-1α) is able to regulate VEGF in pituitary adenomas and other human tumors." (PMID 30733705, 2019). "The current study has profound clinical importance and supports a therapeutic role for HIF-1α in ACTH pituitary adenoma due to its antiapoptotic effects and downregulation of GR." (PMID 26002039, 2015). "Hypoxia inducible factor-1α (HIF-1α) is the central transcriptional regulator of hypoxic responses during the progression of pituitary adenomas." (PMID 26002039, 2015). "Cx43 might play an import part in tumorigenesis of prolactinoma, the relationship between Cx43 and VEGF, HIF-1α in pituitary adenomas requires future investigation." (PMID 30733705, 2019). "Although previous immunohistochemical studies revealed that HIF-1α is expressed in adreno-cortico-tropic-hormone (ACTH) pituitary adenomas, the role of HIF-1α remains unclear." (PMID 26002039, 2015). "A previous article reported that HIF-1α is expressed in ACTH pituitary adenomas." (PMID 26002039, 2015). "In addition, RSUME is involved in pituitary adenoma progression by means of initiating pituitary tumor neovascularization through regulating HIF-1α levels and subsequent VEGF-A production under hypoxia in murine pituitary tumor cell lines and human pituitary adenoma cells." (PMID 35528020, 2022). "Therefore, we suggest that siRNA targeting HIF-1α may have potential therapeutic value in treating ACTH pituitary adenoma." (PMID 26002039, 2015). "There is overexpression of RSUME, HIF-1α, and VEGF-A in invasive pituitary adenoma surgical specimens compared with non-invasive ones, confirming RSUME as an upstream regulator of expression after the HIF-1α knockdown." (PMID 30733705, 2019). "Indeed, RSUME plays an important role in initiating pituitary tumor neovascularization through regulating HIF-1α levels and subsequently VEGF-A production and may, therefore, be involved in pituitary adenoma progression." (PMID 29615979, 2018). "However, the roles of HIF-1α in the development and clinical presentation of ACTH pituitary adenomas remain unknown." (PMID 26002039, 2015).
pituitary tumor (10 papers, 2015 to 2025). A benign or malignant neoplasm affecting the pituitary gland. "Another group reported that Hif-1α activates protein kinase A by repressing RIIβ subunit transcription in human GH-secreting pituitary tumor cells; HIF-1α represses the transcription of the gene encoding RIIβ (PRKAR2B)." (PMID 36147561, 2022). "In fact, we found that the stimulatory effect of HIF-1α on PKA activity in GH-secreting pituitary tumor cells occurs specifically through suppression of RIIβ." (PMID 32111982, 2020). "In primary human tumor cell cultures as well as immortalized pituitary tumor cells, hypoxia, and HIF-1α increased PKA activity and its downstream targets CREB and GH synthesis without affecting intracellular cAMP concentrations." (PMID 32111982, 2020). "Hif-1α regulated VEGF only in certain conditions, e.g. HIF-1α induced VEGF production in pituitary tumour cells 33, and activated HIF-1α promotes VEGF synthesis in mesenchymal stem cells." (PMID 25823960, 2015). "It was reported that HIF1A can suppress the transcription of PKA regulatory subunit 2B (PRKAR2B) by sequestering SP1 from the PRKAR2B promoter in human growth hormone–secreting pituitary tumors." (PMID 40493409, 2025). "However, HIF-1α co-immunoprecipitated with Sp1 in hypoxic GH3 cells confirming their physical interaction in pituitary tumor cells." (PMID 32111982, 2020). "Indeed in GH-secreting pituitary tumors from patients with acromegaly (n = 10), we confirmed a significant decrease in PRKAR2B expression and a significant increase in HIF-1a expression compared with normal anterior pituitary glands and this was also shown at protein level." (PMID 32111982, 2020). "Immunohistochemistry performed on archival paraffin embedded GH-secreting pituitary tumors from patients with acromegaly and normal autoptic pituitary samples showed abundant nuclear HIF-1α staining in acromegalic tumors and virtually absent staining in the normal pituitary." (PMID 32111982, 2020). "Similarly, immortalized GH-secreting pituitary tumor GH3 cells incubated under hypoxic conditions showed increased rat Gh promoter activity, transcription and hormone secretion, and these effects were abrogated by knocking down HIF-1α with RNA-interference." (PMID 32111982, 2020). "In addition, we observed a significant negative correlation between HIF-1α protein and PRKAR2B mRNA levels in the GH-secreting pituitary tumors." (PMID 32111982, 2020). "Additionally, PPARα, PGC-1α, and FOXO1 ligands linked to acetylcarnitine may participate in the signaling pathways of prolactinoma, while SREBP-1c, LXRα/β, PPARγ, HIF-1α, PPARα, PGC-1α, and FOXO1 are likely involved in the signaling of nonfunctional pituitary tumors." (PMID 39669498, 2024).
retinoblastoma (10 papers, 2016 to 2025). A malignant tumor that originates in the nuclear layer of the retina. "It has been reported that LRPPRC promotes retinoblastoma progression and glycolysis by targeting HIF-1α, which is corroborates with our results." (PMID 40775462, 2025). "In hypoxic conditions, hypoxia promotes the invasion of retinoblastoma HXO-RB44 cells by activating the HIF-1α/MMP9 signaling pathway." (PMID 36118887, 2022). "Oncogenic TMPO-AS1 was also abnormally up-regulated in retinoblastoma tissues which served as ceRNA to modulate the expression of HIF-1α, a core hub regulating cellular lactate metabolism by sponging miR199a-5p." (PMID 35422758, 2022). "CNMs inhibit retinoblastoma growth in a xenograft mouse model by suppressing tumor angiogenesis which may be related to an inhibition in the HIF-1α/VEGF pathway." (PMID 32091275, 2020). "Gao Y showed that BDNF could induce a higher expression of HIF-1α via the activation of TrkB in human Y-79 retinoblastoma cells, which consequently contributed to its effect against chemotherapeutic agent-induced cytotoxicity and apoptosis." (PMID 27852063, 2016). "Collectively, these data showed MDM2 and HIF-1α are of great importance in the generation of CSCs in RB and inhibition of these 2 proteins could significantly decrease the stem-cell properties of primary retinoblastoma cells." (PMID 36741966, 2023). "In conclusion, our results reveal that CNMs target the HIF-1α/VEGF pathway, which may be an important reason for the suppression of retinoblastoma growth and angiogenesis." (PMID 32091275, 2020).
Right ventricular hypertrophy (10 papers, 2011 to 2025). In this case the right ventricle is more muscular than normal, causing a characteristic boot-shaped (coeur-en-sabot) appearance as seen on anterior- posterior chest x-rays. "Heterozygous HIF-1α+/– mice subjected to chronic hypoxic exposure remarkably lack elevated pulmonary arterial pressure and right ventricular hypertrophy." (PMID 31083380, 2019). "Remarkably, heterozygous Hif1α+/- or Hif2α+/- mice showed a reduced increase in pulmonary arterial pressure and right ventricular hypertrophy upon exposure to chronic hypoxia in comparison with wild type mice." (PMID 23451260, 2013). "Interestingly, the expression of HIF-1α and PDGF was not only elevated and positively associated with each other in the lungs of the HIV-1 Tg rats, but the quantity of each was directly related, in a linear fashion, to the degree of increase in the right ventricular hypertrophy (RV/LV+septum ratio)." (PMID 21819559, 2011). "Simultaneously, the absence of HIF-1α in smooth muscle cells attenuated the rise in RV systolic pressure induced by chronic hypoxia, without improving right ventricular hypertrophy." (PMID 38164358, 2024).
skin infection (10 papers, 2015 to 2024). An inflammatory process affecting the skin, caused by bacteria, viruses, parasites, or fungi. "Our finding of impaired antibacterial defense in LysM-cre × Hif1αfl/fl mice is corroborated by a study reporting the importance of myeloid HIF1α for limiting the systemic spread of bacteria during skin infection by group A streptococci." (PMID 34393650, 2021). "Reactive oxygen species (ROS) are mainly generated by mitochondria and can be protective against skin infection by activating hypoxia-inducible factor 1-alpha (HIF1α) and recruiting immune cells." (PMID 34487917, 2021). "This implements mitochondrial reactive oxygen species (ROS) signalling in the defence against skin infection through hypoxia-inducible factor 1-alpha (HIF1α) activation and immune cell recruitment." (PMID 31083540, 2019). "AKB-4924 (Aerpio Therapeutics) is a prolyl-hydroxylase inhibitor drug candidate that preferentially stabilizes HIF-1α and increases phagocyte killing of S. aureus in vitro and in a murine skin infection model." (PMID 25927232, 2015). "Likewise, the use of mimosine, a HIF-1α agonist, can boost the ability of phagocytes and whole blood to kill S. aureus and can reduce lesion size in a murine model of skin infection." (PMID 30082478, 2018).
tuberculosis (10 papers, 2013 to 2026). A chronic, recurrent infection caused by the bacterium Mycobacterium tuberculosis. "By targeting the GSK3β/HIF-1α axis, this study presents a potential strategy for managing other intracellular infections, including tuberculosis and chronic viral diseases, where hypoxia signaling is critical." (PMID 41509906, 2026). "Stabilization of HIF1A promotes migration of tolerogenic dendritic cells (DCs) and monocyte-derived DCs (Mo-DCs) from tuberculosis (TB) patients." (PMID 38922679, 2024). "HIF1A activation in CD16+ monocytes from tuberculosis (TB) patients leads to dendritic cells (DCs) with poor migration capacity." (PMID 38922679, 2024). "The role of HIF1a in tuberculosis is ambiguous: it promotes antimicrobial activity of human macrophages against M.tb, but also impairs CD4 T cell activation and differentiation, leading to increased susceptibility to M.tb infection." (PMID 37834286, 2023). "Stabilization of Hif-1α therefore represents a potential target for therapeutic intervention against tuberculosis." (PMID 24367256, 2013). "Furthermore, HIF-1α inhibition could be a therapeutic alternative for the treatment of tuberculosis, as it increased the immune response against Mtb." (PMID 35453567, 2022). "Tuberculous granuloma formation is mediated by hypoxia-inducible factor 1 alpha (HIF-1α), and is essential for establishing latent tuberculosis infection (LTBI) and its progression to active tuberculosis (TB)." (PMID 35453567, 2022).
Ureteral obstruction (10 papers, 2013 to 2025). Obstruction of the flow of urine through the ureter. "Genetic ablation of proximal tubule epithelial HIF1α appears to impede the development of kidney fibrosis in unilateral ureteral obstruction in mice." (PMID 35966094, 2022). "Similarly, the genetic ablation of Hif1α in the renal proximal tubule inhibited tubulointerstitial fibrosis in the in vivo model of unilateral ureteral obstruction." (PMID 28774305, 2017). "A protective role of HIF‐1α is reported in a model of unilateral ureteral obstruction (UUO)." (PMID 23778187, 2013). "For example, the global inactivation of the Vhlh gene by the Cre-loxP system resulted in HIF-1α and HIF-2α stabilization and suppressed fibrogenesis in mice subjected to unilateral ureteral obstruction." (PMID 28774305, 2017). "In conclusion, the treatment with the small extracellular vesicles secreted by bone marrow mesenchymal stromal cells from trained rats carries pro-angiogenic miR-296 and delivers them into rats subjected to unilateral ureteral obstruction, possibly corroborating angiogenesis, via CD34 and HIF-1α." (PMID 34925478, 2021). "In line with our observations are studies where the global Hif1α deletion using the Ubc-cre/ERT2 system did not affect collagen accumulation, although inflammation and renal injury were enhanced by Hif1α deletion in the model of unilateral ureteral obstruction." (PMID 28774305, 2017).
breast adenocarcinoma (9 papers, 2013 to 2025). "Studies on intensity of apoptosis using the TUNEL approach demonstrated that level of apoptosis in canine mammary adenocarcinomas manifested positive correlation with expression of HIF-1α protein and the correlation demonstrated a high level (r = 0.62; P < 0.0001)." (PMID 24153191, 2013). "Similarly, in our investigations on canine mammary adenocarcinomas we have found that an increased HIF-1α expression was paralleled by higher levels of apoptosis among neoplastic cells." (PMID 24153191, 2013). "Furthermore, these experiments suggest that HIFα paralog induction in metastatic nodules depends on diffusion‐limiting hypoxia, since identically sized liver or lung metastases from colon or breast adenocarcinomas both expressed HIF‐1α, an induction that was offset by LDM chemotherapies." (PMID 32686360, 2020). "In this study, we confirmed the expression levels of HIF-1α, IGF-1R and TOP2A proteins in mammary adenocarcinomas tissue." (PMID 40969744, 2025). "To examine whether this reduction of hypoxia-induced HIF-1α accumulation by NDV also occurs in other cancer cell lines, we repeated the experiment with MCF-7 breast adenocarcinoma cells." (PMID 27902314, 2016). "HIF1α removal in macrophages has been shown to lead to a decrease in tumor growth in the model of spontaneous breast adenocarcinoma PYMT, which is the result of an improvement in the proliferative ability and function of lymphocytes in the absence of myeloid HIF1α." (PMID 34885171, 2021).
Burkitt lymphoma (9 papers, 2013 to 2024). A rare form of malignant mature B-cell non-Hodgkin lymphoma. "Our data indicate that LMP2A increases ATP generation in multiple Burkitt lymphoma cell lines that were dependent on HIF-1α." (PMID 38612754, 2024). "Relevant to the present results, selective induction of HK2 and pyruvate dehydrogenase kinase-1 (PDK1) by hypoxia (and HIF-1α and c-myc) was observed in a previous study of human P493-6 B-lymphoblastoid cells, a model for human Burkitt’s lymphoma." (PMID 23866118, 2013). "It is known that the hypoxia-inducible factor 1-alpha (HIF1A) and MYC proteins cooperatively regulate expression of the HK2 and PDK1 genes, respectively, in the Burkitt lymphoma (BL) cell line P493-6, carrying an inducible MYC gene repression system." (PMID 26312753, 2015). "In Burkitt lymphoma, in which both MYC and HIF1α are highly expressed, HIF1α can actually collaborate with MYC to induce the expression of specific target genes, such as HK2, PDK1, and vascular endothelial growth factor (VEGF) under hypoxia and confer resistance to cisplatin treatment." (PMID 33251216, 2020). "A similar analysis of 17 EBV+ endemic Burkitt lymphomas indicated HIF-1α mRNA was, on average, nine-fold more abundant than HIF-2α mRNA (range 2-fold to 19-fold), with HIF-3α mRNA detectable above background in only one of these 17 tumors (at 1/20th of the HIF-1α level)." (PMID 28617871, 2017). "We first determined the HIF-1α protein levels in PEL lines BCBL-1 and BC-3 and a virus-negative Burkitt’s lymphoma (BL) line BJAB." (PMID 28922425, 2017). "Using the virus-negative Burkitt’s lymphoma cell line BJAB, which does not express HIF-1α under normoxic conditions, as a control, HIF-1α in the PEL cell lines BCBL-1 and BC-3 could remarkably affect the growth metabolism, viral replication, and expression of viral-encoded oncogenes in PEL cells." (PMID 37588219, 2024).
colorectal adenocarcinoma (9 papers, 2008 to 2025). The most common type of colorectal carcinoma. "Hydroxytyrosol induced functional impairment of the hypoxia inducible factor-1alpha (HIF-1α)/microsomal prostaglandin-E synthase-1 (mPGEs-1)/PGE-2/VEGF axis in HT-29 and WiDr human colorectal adenocarcinoma cells." (PMID 34578851, 2021). "In a previous study on the expression of hypoxia-related markers (HIF1α, HIF2α, CA9 and GLUT1) in colorectal adenocarcinomas, we found that in all tumours at least one of these proteins is immunohistochemically expressed." (PMID 18728663, 2008).